NEDD8 (NEDD8 ubiquitin like modifier)
Description:
Attachment of NEDD8 to cullins is critical for the recruitment of E2 to the cullin-RING-based E3 ubiquitin-protein ligase complex, thus facilitating polyubiquitination and proteasomal degradation of cyclins and other regulatory proteins. Covalent attachment to its substrates requires prior activation by the E1 complex UBE1C-APPBP1 and linkage to the E2 enzyme UBE2M. Neddylates EGFR resulting in protein stabilization and translocation to the cell membrane.
Synonyms: NEDD-8
Tractability: Small molecule: a structure with a bound ligand is known. PROTAC: ubiquitination databases record sites on it; its protein half-life has been measured; a small molecule that binds it is known.
Chemical probes: PEVONEDISTAT (high quality)
Gene: Protein-coding gene on chromosome 14 (24,216,802 to 24,232,385, reverse strand). Ensembl gene ENSG00000129559.
Subcellular location: Nucleus
Subcellular location (Human Protein Atlas): Nucleoplasm; Cytosol; Golgi apparatus
Pathways (Reactome):
Metabolism of proteins: Neddylation; UCH proteinases
Signal Transduction: TGF-beta receptor signaling activates SMADs
Transport of small molecules: Iron uptake and transport
Vesicle-mediated transport: Cargo recognition for clathrin-mediated endocytosis
Gene Ontology:
Molecular function: protein binding; ubiquitin protein ligase binding; protein tag activity
Biological process: protein neddylation; anatomical structure morphogenesis; modification-dependent protein catabolic process; protein modification process; protein ubiquitination; proteolysis; regulation of proteolysis; ubiquitin-dependent protein catabolic process; cellular response to camptothecin; regulation of postsynapse assembly
Cellular component: extracellular exosome; nucleoplasm; cytoplasm; cytosol; nucleus; glutamatergic synapse; postsynapse
Genetic constraint (gnomAD): Loss-of-function variants: 1 observed, 13.48 expected, observed/expected ratio (o/e) 0.0742, 90% interval 0.025 to 0.35. The upper end of that interval is the gene's LOEUF score, 0.35, which puts it in group 1 of 6, group 1 being the genes least tolerant of losing a copy. Missense variants: 10 observed, 96.94 expected, observed/expected ratio (o/e) 0.1, 90% interval 0.063 to 0.17. Synonymous variants: 31 observed, 33.8 expected, observed/expected ratio (o/e) 0.92, 90% interval 0.69 to 1.24.
Homologues: Orthologues: dog NEDD8 (100% identical), rabbit NEDD8 (100% identical), mouse Nedd8 (99% identical), rat Nedd8 (99% identical), guinea pig NEDD8 (98% identical), zebrafish nedd8l (94% identical), tropical clawed frog nedd8 (93% identical), zebrafish nedd8 (93% identical), Drosophila melanogaster Nedd8 (88% identical), pig NEDD8 (88% identical), Caenorhabditis elegans ned-8 (83% identical). Paralogues in human: UBA52 (57% identical), UBC (57% identical), RPS27A (54% identical), ANKUB1 (38% identical), ZFAND4 (33% identical), UBD (26% identical), UBL4A (25% identical), ISG15 (23% identical), UBL4B (23% identical), UBB (2% identical).
Diseases named in the same sentence as NEDD8 in open-access papers:
NEDD8 is named in the same sentence as 82 diseases in open-access papers, as found by Europe PMC text mining. Sharing a sentence is not in itself a finding about the gene and the disease. The quoted sentences say what the papers report.
breast cancer (13 papers, 2017 to 2026). A primary or metastatic malignant neoplasm involving the breast. "Here the authors show that NEDD8 loss in breast cancer cells is associated with enhanced immunogenicity and increased sensitivity to PD-1 blockade in preclinical cancer models." (PMID 38678024, 2024). "Despite the low patient number, NEDD8 mRNA expression show association to pathologic complete response rates in breast cancer patients receiving chemo-immunotherapy." (PMID 38678024, 2024). "Neddylation has been reported to be activated in a variety of tumors, and we noted higher expression of UBC12 (E2 for NEDD8 transfer) in breast cancer tissues compared to normal tissues in The Cancer Genome Atlas (TCGA) database." (PMID 38926803, 2024). "Expression of the Nedd8 gene was disabled using CRISPR/Cas9 in a murine breast cancer cell line, EO771." (PMID 38678024, 2024). "Consistent with mRNA analysis, the results of immunohistochemistry revealed that HER2 and NEDD8 were highly expressed in breast cancer tissues." (PMID 36632463, 2023). "We first analyze the published microarray dataset and found that NEDD8 is overexpressed in breast cancer." (PMID 36632463, 2023). "Collectively, this study demonstrates a previously undiscovered role of NEDD8-dependent HER2 neddylation promotes tumor growth in breast cancer." (PMID 36632463, 2023). "Recently, PTEN, a well-known tumor suppressor, was identified as a novel target for modification with NEDD8, and PTEN neddylation has been associated with tumor development in all types of breast cancers." (PMID 33996822, 2021). "To investigate the status of NEDDylation pathway in breast cancer, we first determined the expression levels of NEDD8 in the MCF7, T47D, MDA-MB-231 and MCF10A cells." (PMID 32839427, 2020). "Therefore, analysis of these published gene expression data indicates a potential role of NEDD8 in controlling HER2+ breast cancer." (PMID 36632463, 2023). "To determine whether HER2 is a substrate protein of NEDD8, we first used RNAi to inhibit NEDD8 expression in two HER2-positive breast cancer cell lines (BT474 and SK-BR3)." (PMID 36632463, 2023). "In breast cancer tissues, NEDD8 mRNA levels were higher than healthy tissues and adjacent tissues." (PMID 36632463, 2023). "To further examine whether HER2 is responsible for neddylation-mediated breast cancer progression, we tested the signaling pathways related with ErbB2/NEDD8 using multi-omics analysis." (PMID 36632463, 2023). "The high levels of SUMO2, ISG15, NEDD8, and UBD are related to worse prognosis outcomes in breast cancer." (PMID 41583390, 2026). "Next, we recruited breast cancer patients to detect the expression of NEDD8 and HER2 proteins in human breast cancer." (PMID 36632463, 2023). "Overexpressed NEDD8 and NAE1 are positively correlated with HER2 expression in human breast cancer." (PMID 36632463, 2023). "In breast cancer there is growing preclinical evidence of the role of ubiquitin and ubiquitin-like SUMO and Nedd8 peptide conjugation to the proteome in tumorigenesis and drug resistance, particularly through their interplay with estrogen receptor signaling and DNA repair." (PMID 33671201, 2021). "The result showed that NEDD8 was overexpressed in the breast cancer cell lines tested compared to the non-cancerous breast epithelial MCF10A cells." (PMID 32839427, 2020). "We also found that neither the SPOP-ASCT2 axis, nor NEDD8 and few neddylation enzymes, including E1 heterodimer NAE1/APPBP1, and UBA3/NAEβ, and two E2s, UBE2M and UBE2F is subjected to regulation by glucose deprivation in breast cancer cells." (PMID 35641493, 2022).
glioblastoma (10 papers, 2017 to 2024). The most malignant astrocytic tumor (WHO grade IV). "NAE1 and UBA3 levels increased in glioblastoma patients; high NEDD8 levels were associated with poor clinical outcomes." (PMID 31771104, 2019). "Additionally, a high expression level of NEDD8 is associated with the poor survival of glioblastoma patients." (PMID 31771104, 2019). "This is most likely to occur when NEDD8 is overexpressed in diseases like glioblastoma and osteosarcoma." (PMID 33918652, 2021). "Glioblastoma had the greatest negative correlation between UBA1 and NEDD8 (R = −0.5184), consistent with reports showing up-regulation of NEDD8 in glioblastoma." (PMID 34685640, 2021). "Quantitative results showed that expression of NEDD8 was about 40-80% higher in glioblastoma than in normal samples (right)." (PMID 31771104, 2019). "NEDD8 expression was significantly upregulated in glioblastoma compared to the expression level of normal samples." (PMID 31771104, 2019). "Next, we verified the level of NEDD8 protein in glioblastoma using Immunohistochemistry (IHC) staining of Formalin-fixed paraffin-embedded (FFPE) samples from various patient-derived xenograft models." (PMID 31771104, 2019). "We first analyzed public data to determine whether NEDD8 pathway proteins are important in glioblastoma development and patient survival." (PMID 31771104, 2019). "Given a recent proteomics report showing that NEDD8 is downregulated in prostate cancer tissues versus normal prostate tissues, we examined whether the downregulation of NEDD8 is associated with cell migration in a prostate cancer cell-line PC3 and in a glioblastoma cell-line U373MG." (PMID 29301501, 2018). "Several recent studies have observed a correlation between overactivation of NEDD8 pathway components, including NEDD8, UBA3, NAE1, and Ubc12, with cancer progression and poor prognosis in human lung cancers, colorectal cancers, and glioblastomas." (PMID 28475037, 2017).
colorectal cancer (8 papers, 2017 to 2024). A primary or metastatic malignant neoplasm that affects the colon or rectum. "Furthermore, we also detected the enhanced expression of NEDD8 in PBMC from colorectal cancer patients after surgery." (PMID 38177106, 2024). "Increased NEDD8 levels along with increased levels of enzymes in the NEDD8 activation and conjugation pathway such as NAE1 have been detected in numerous cancer types, such as pancreatic cancer, osteosarcoma, bladder, and colorectal cancers to name but a few." (PMID 34685640, 2021). "Interestingly, in the case of colorectal cancers, a non-canonical target of NEDD8 was identified." (PMID 34685640, 2021).
lung carcinoma (5 papers, 2017 to 2022). "Besides, to gain an insight of DNA-PKcs and NEDD8 relationship, we also compared the expression profile of DNA-PKcs and NEDD8 in four independent lung cancer gene expression data sets from GEO database, and significant correlation was found as indicated." (PMID 32457294, 2020).
prostate carcinoma (5 papers, 2014 to 2023). A carcinoma that arises from epithelial cells of the prostate gland. "Our results confirmed there was a significant decrease in NEDD8 mRNA in prostate cancer tissues compared to normal tissues." (PMID 33097763, 2020). "NEDD8 mRNA levels in prostate cancer significantly decreased while those of lung tumor and ovarian tumor did not." (PMID 33097763, 2020). "FKB inhibits NEDD8 conjugations to both Cullin1 and Ubc12 in prostate cancer cell lines and Ubc12 neddylation in an in vitro assay." (PMID 30885218, 2019). "In this study, we have shown that FKB inhibits NEDD8 conjugations to both Cullin1 and Ubc12 in prostate cancer cell lines and Ubc12 NEDDylation in an in vitro assay." (PMID 30885218, 2019). "Given a recent proteomics report showing that NEDD8 is downregulated in prostate cancer tissues versus normal prostate tissues, the authors were encouraged to investigate the role of NEDD8 in prostate cancer promotion." (PMID 29301501, 2018). "Given a recent proteomics report showing that NEDD8 is downregulated in prostate cancer tissues versus normal prostate tissues, we tested the possibility that neddylation plays a role in cancer evolution, and then tried to identify target proteins of the neddylation." (PMID 29301501, 2018). "In addition, both conjugated and free NEDD8 were revealed to be highly expressed in prostate cancer cells." (PMID 25093192, 2014).
esophageal squamous cell carcinoma (4 papers, 2019 to 2022). Esophageal squamous cell carcinoma (ESCC) is a type of esophageal carcinoma (EC) that can affect any part of the esophagus, but is usually located in the upper or middle third. "We aimed to study whether NEDD8 (neural precursor cell expressed, developmentally down-regulated 8) might serve as a therapeutic target in esophageal squamous cell carcinoma (ESCC)." (PMID 33733647, 2021).
Hepatic steatosis (4 papers, 2020 to 2025). Steatosis is a term used to denote lipid accumulation within hepatocytes. "Previous findings showed that the levels of NEDD8 protein were increased in patients with hepatic steatosis compared to those in healthy controls." (PMID 36432651, 2022). "The expression levels of NEDD8 mRNA are higher in liver tissues of hepatic steatosis patients than those of healthy subjects." (PMID 32332706, 2020). "To further examine whether NEDD8 is involved in hepatic steatosis, we analyzed NEDD8, SREBP1c, and LXRα protein levels in the liver tissues from hepatic steatosis patients and normal subjects." (PMID 32332706, 2020). "Given that NEDD8 is highly expressed in NAFLD patients and neddylation enhances SREBP1c-mediated hepatic lipogenesis through blockade of its ubiquitination, our results provide a clue to understand how SREBP1c contributes to the hepatic steatosis development." (PMID 32332706, 2020).
hepatocellular carcinoma (4 papers, 2015 to 2025). A malignant tumor that arises from hepatocytes. "Further analysis found that the three proteins (UBC12, NEDD8, and SREBP1) were up-regulated in hepatocellular carcinoma (HCC) compared to non-tumorous tissue." (PMID 38560498, 2024).
liver cancer (4 papers, 2018 to 2024). An epithelial or non-epithelial malignant neoplasm that arises from the liver. "Intriguingly, the use of MLN4924, a specific neddylation inhibitor that forms a stable MLN4924-NEDD8 adduct by binding to NEDD8, has been shown to decrease lipid accumulation by suppressing SREBP1 neddylation in liver cancer cells." (PMID 39551780, 2024).
melanoma (4 papers, 2004 to 2024). A malignant, usually aggressive tumor composed of atypical, neoplastic melanocytes. "In the current study, it was identified that there was increased expression of NEDD8 conjugates in melanoma tissues, which indicates the close association between the neddylation pathway and melanoma." (PMID 24765193, 2014). "During our experimentation with MLN4924, we found that inhibition of the NEDD8 pathway in A375 melanoma cells dramatically decreases the protein levels of Mdmx, but not of Mdm2." (PMID 39404389, 2024). "A recent study has revealed a large number of NEDD8-target molecules related to cell survival using a proteomic approach in A375 melanoma cells." (PMID 28216678, 2017). "In this study, NEDD8 conjugation was detected in all seven cases of melanoma and in the normal tissues around them." (PMID 24765193, 2014). "The results from seven samples of melanoma showed that NEDD8 conjugation in melanoma tissues was higher than that in the normal tissues surrounding the melanoma." (PMID 24765193, 2014). "In the present study, expression levels of conjugated NEDD8 were examined in melanoma tissues to confirm the results of our previous research." (PMID 24765193, 2014). "In our previous study, it was identified that NEDD8 conjugation was upregulated in melanoma cell lines." (PMID 24765193, 2014). "In the current study, conjugated NEDD8 expression was also demonstrated to be upregulated in melanoma tissue." (PMID 24765193, 2014). "It has been hypothesized that interfering with the expression of UBA3 may inhibit NEDD8 conjugation and, subsequently, prevent the proliferation of melanoma." (PMID 24765193, 2014). "With the exception of NEDD8 and UCHL3 in the M14 cell line, all the other enzymes, which correlated closely with neddylation, were upregulated in the three melanoma cell lines." (PMID 24765193, 2014).
nasopharyngeal carcinoma (4 papers, 2017 to 2024). A carcinoma arising from the nasopharyngeal epithelium. "In addition, inhibition of autophagy mediated by HMGB1, LMP1, or NEDD8 also promoted treatment responses to IR in ESCC, nasopharyngeal carcinoma and oral squamous cell carcinoma, respectively." (PMID 38783335, 2024).
viral infections (4 papers, 2010 to 2025). "Both SUMO and Nedd8 are two well-studied UBLs: SUMO is involved in several cellular activities, including cell cycle control, nuclear transport and responses to viral infections, and Nedd8 functions in the regulation of E3 ubiquitin-protein ligases." (PMID 32296577, 2020). "In particular, the role of several ubiquitin-like modifications in orthoflaviviral infection, such as NEDD8, FAT10, and UFM1, have yet to be described, although they do have roles in other viral infections." (PMID 40007042, 2025). "However, to our knowledge, inhibition of CRLs through a pathogen's protein binding to NEDD8 has never been reported in the pathogenesis of bacterial or viral infections." (PMID 20941356, 2010).
osteosarcoma (3 papers, 2021 to 2025). A usually aggressive malignant bone-forming mesenchymal neoplasm, predominantly affecting adolescents and young adults. "Studies have demonstrated that NUB1 overexpression can inhibit the growth of a wide range of tumors, including renal cell carcinoma, osteosarcoma, and gastric cancer, by inhibiting NEDD8 and its conjugation system." (PMID 40164590, 2025). "In addition, studies have revealed that NUB1 knockdown promotes tumor growth in renal cell carcinoma, osteosarcoma, and gastric cancer by upregulating NEDD8 and its conjugation system." (PMID 40164590, 2025).
Parkinson disease (3 papers, 2012 to 2024). A progressive degenerative disorder of the central nervous system characterized by loss of dopamine producing neurons in the substantia nigra and the presence of Lewy bodies in the substantia nigra and locus coeruleus. "NEDD8 conjugation has also been implicated in neurodegenerative disorders, such as in formation of the abnormal protein inclusion bodies in Parkinson disease." (PMID 23118980, 2012). "In Parkinson’s disease, specific immunoreactivity to NEDD8 was detected in Lewy bodies, suggesting that protein neddylation is involved in the pathogenesis of Parkinson’s disease." (PMID 39564524, 2024). "Moreover, NEDD8 also accumulates in aggregated inclusion bodies in neuronal cytoplasm of patients with Parkinson’s, amyotrophic lateral sclerosis, and dementia with Lewy bodies, much as it does in AD." (PMID 31882005, 2019).
renal cell carcinoma (3 papers, 2022 to 2025). "NEDD8 serves as a crucial marker of neddylation, and its reduced expression indicates that MLN4924 effectively inhibits neddylation modification in renal cell carcinoma." (PMID 38794205, 2024).
breast tumor (2 papers, 2010 to 2024). "In order to dissect immunological changes in Nedd8-deficient breast tumors, we analyzed intra-tumoral immune cell population and mRNA gene signatures using flow cytometry and the Nanostring technology, respectively." (PMID 38678024, 2024). "In this study, we used our assay to 1) identify novel substrates of the SCFSkp2 ubiquitin ligase, 2) profile ubiquitin, SUMO1, and NEDD8 conjugation activities of whole-cell extracts, and 3) define changes in ubiquitylation activity that associate with human breast tumor progression." (PMID 20596523, 2010).
gastric cancer (2 papers, 2023 to 2025). A primary or metastatic malignant neoplasm involving the stomach. "The novel indole derivative V7 could also inhibit the coupling of UBC12 and NEDD8 by binding to NAE to inhibit the proliferation of gastric cancer cells and induce apoptosis by inhibiting neddylation and the MAPK pathway." (PMID 37777749, 2023).
head and neck squamous cell carcinoma (2 papers, 2021 to 2023). A squamous cell carcinoma that arises from any of the following anatomic sites: lip and oral cavity, nasal cavity, paranasal sinuses, pharynx, larynx, and salivary glands. "Since oral cancer is a head and neck squamous cell carcinoma (HNSCC), we first delineated the association of NEDD8 expression with HNSCC tumorigenesis." (PMID 36890567, 2023).
leukemia (2 papers, 2014 to 2021). A malignant (clonal) hematologic disorder, involving hematopoietic stem cells and characterized by the presence of primitive or atypical myeloid or lymphoid cells in the bone marrow and the blood. "NEDD8 and RBX1 inhibition by the small molecule inhibitor pevonedistat inhibited leukemia cell growth." (PMID 34857808, 2021).